CCIN (calicin)
Description:
Required for both nuclear and acrosomal shaping during spermiogenesis.
Synonyms: KBTBD14; BTBD20; SPGF91
Tractability: No criterion of Open Targets' tractability assessment is met for any kind of drug.
Gene: Protein-coding gene on chromosome 9 (36,169,388 to 36,171,334, forward strand). Ensembl gene ENSG00000185972.
Subcellular location: Cytoplasm, cytoskeleton, perinuclear theca, calyx
Subcellular location (Human Protein Atlas): Calyx; Nucleoplasm; Perinuclear theca
Gene Ontology:
Molecular function: protein binding; ubiquitin-like ligase-substrate adaptor activity
Biological process: spermatogenesis; proteasome-mediated ubiquitin-dependent protein catabolic process; spermatid development
Cellular component: cytoskeletal calyx; nucleus; perinuclear theca; sperm glycocalyx; Cul3-RING ubiquitin ligase complex; cytoplasm
Genetic constraint (gnomAD): Loss-of-function variants: 15 observed, 33.83 expected, observed/expected ratio (o/e) 0.44, 90% interval 0.3 to 0.68. The upper end of that interval is the gene's LOEUF score, 0.68, which puts it in group 2 of 6, group 1 being the genes least tolerant of losing a copy. Missense variants: 623 observed, 797.29 expected, observed/expected ratio (o/e) 0.78, 90% interval 0.73 to 0.83. Synonymous variants: 302 observed, 313.24 expected, observed/expected ratio (o/e) 0.96, 90% interval 0.88 to 1.06.
Homologues: Orthologues: chimpanzee CCIN (99% identical), macaque CCIN (98% identical), mouse Ccin (93% identical), rat Ccin (93% identical), rabbit CCIN (93% identical), pig CCIN (92% identical). Paralogues in human: KLHL5 (23% identical), KLHL35 (22% identical), KLHL21 (22% identical), KLHL1 (22% identical), KLHL6 (22% identical), KLHL28 (22% identical), KLHL4 (22% identical), GAN (21% identical), KLHL12 (21% identical), KLHL20 (21% identical), KLHL30 (20% identical), KLHL10 (20% identical), and 42 more.
Diseases named in the same sentence as CCIN in open-access papers:
CCIN is named in the same sentence as 4 diseases in open-access papers, as found by Europe PMC text mining. Sharing a sentence is not in itself a finding about the gene and the disease. The quoted sentences say what the papers report.
Globozoospermia (5 papers, 2016 to 2024). Any structural anomaly of the acrosome resulting in a round sperm head. "Calicin is one of the subacrosomal cytoskeletal proteins involved in acrosomal biogenesis which its absence results in globozoospermia." (PMID 30291685, 2019). "In addition to mutations in genes already linked to globozoospermia in mice, we identified variants in novel genes C2CD6 (c.338A > G; p.(His113Arg)), CCIN (c.853G > A; p.(Gly285Ser)) and C7orf61 ((c.259del; p.(Glu87Argfs*46)), with a clear link to acrosome biology." (PMID 31985809, 2020). "Only, four genes have been so far detected in individuals presenting globozoospermia including DPY19L2, SPATA16, PICK1 and Calicin." (PMID 30291685, 2019).
infertile (2 papers, 2023 to 2024). "Importantly, we further report that three infertile men with sperm head deformities carry homozygous pathogenic mutations in CCIN, and the corresponding Ccin-mutant mice mimic the phenotype in patients." (PMID 38573307, 2024).
male infertility (1 paper, 2023). The inability of the male to effect fertilization of an ovum after a specified period of unprotected intercourse. "Intersection of genes from transcriptomic studies with genes with identified rare variants revealed a total of 7 genes linked with male infertility phenotype (CYP11A1, CYP17A1, RSPH3, TSGA10, AKAP4, CCIN, NDNF)." (PMID 37670815, 2023). "According to the literature, there has been limited evidence for the association of AKAP4, CCIN and NDNF genes with male infertility." (PMID 37670815, 2023).
CCIN also shares sentences with these, for which no sentence is quoted: macrozoospermia (1 paper).